SERF1B (small EDRK-rich factor 1B)
Description:
Positive regulator of amyloid protein aggregation and proteotoxicity. Induces conformational changes in amyloid proteins, such as APP, HTT, and SNCA, driving them into compact formations preceding the formation of aggregates.
Synonyms: h4F5; FAM2B; H4F5C
Gene: Protein-coding gene on chromosome 5 (70,025,251 to 70,043,113, forward strand). Ensembl gene ENSG00000205572.
Subcellular location: Cytoplasm, cytosol; Nucleus
Subcellular location (Human Protein Atlas): Nuclear bodies
Gene Ontology:
Molecular function: protein binding
Biological process: amyloid fibril formation; protein destabilization; nervous system development
Cellular component: cytosol; nucleus; protein-containing complex
Homologues: Orthologues: macaque SERF1B (74% identical). Paralogues in human: SERF1A (36% identical).
Diseases named in the same sentence as SERF1B in open-access papers:
SERF1B is named in the same sentence as 4 diseases in open-access papers, as found by Europe PMC text mining. Sharing a sentence is not in itself a finding about the gene and the disease. The quoted sentences say what the papers report.
male infertility (1 paper, 2023). The inability of the male to effect fertilization of an ovum after a specified period of unprotected intercourse. "We demonstrate our analyses’ potential to identify novel highly germ cell–specific markers (TSPY4 and LUZP4 for spermatogonia; HMGB4 for round spermatids) and identified putatively misregulated genes in male infertility (RWDD2A, CCDC183, CNNM1, SERF1B)." (PMID 36446526, 2023).
cancer (1 paper, 2019). A tumor composed of atypical neoplastic, often pleomorphic cells that invade other tissues. "Finally, lncRNAs such as lnc-EIF2AK4-1:1, -1:4, and -1:5, as well as lnc-SERF1B-1:4 were not correlated with many of the immune-associated or cancer-associated pathways." (PMID 31810243, 2019).
SERF1B also shares sentences with these, for which no sentence is quoted: Infertility (1 paper); pontocerebellar hypoplasia (1).